IL6 (interleukin 6)
Diseases named in the same sentence as IL6 in open-access papers (continued):
Sharing a sentence is not in itself a finding about the gene and the disease.
Castleman disease (continued). "The first-line treatment in unicentric form is mainly surgical, while in idiopathic Castleman disease, anti-interleukin-6 treatment is the therapy of choice." (PMID 39252787, 2024). "Mice that overexpress IL‐6 exhibit a phenotype that resembles the multicenteric Castleman's disease." (PMID 39301097, 2024). "Currently, a monoclonal antibody against IL6, Siltuximab, is approved by the US Food and Drug Administration for the treatment of multicentric Castleman disease." (PMID 37062842, 2023). "Short- and long-term effects of tocilizumab were evaluated in patients with Castleman disease (CD), where chronic elevation of IL-6 produces hepcidin-mediated inflammatory anemia." (PMID 36839968, 2023). "For example, the IL-6 antibody siltuximab have been approved by FDA to treat multicentric Castleman disease." (PMID 36635302, 2023). "The incidence of Castleman disease is also closely related to IL-6 expression, and cases of IgAN combined with Castleman disease, wherein IL-6 antagonist treatment resolves IgAN, have also been reported." (PMID 35870042, 2022). "In rodent experiments, IL-6 transgenic mice displayed features similar to those of patients with Castleman’s disease in that they have multiple lymph node swelling and follicular hyperplasia related to elevated IL-6 production." (PMID 34253862, 2021). "By forming a high-affinity complex with human interleukin-6 (IL-6) to prevent IL-6 from binding to soluble and membrane-bound IL-6 receptors, stuximab is used to treat Castleman’s disease, a type of lymphoproliferative disease." (PMID 34252346, 2021). "In the second approved indication, anti-IL-6 was used in patients with Castleman’s disease, where overproduction of IL-6 from the germinal centers of hyperplastic lymph nodes was described." (PMID 34681685, 2021). "Certain cytokines have been reported in cases of Castleman disease, including IL-6, VEGF, tumor necrosis factor-α(TNF-α), IL-1, and IL-8." (PMID 34208103, 2021). "Emerging evidence indicates that IL-6 signaling inhibition is a beneficial clinical strategy for the treatment of various inflammatory disorders, including RA, Castleman’s disease, and CAR T-cell therapy-induced cytokine storms." (PMID 34253862, 2021). "A possible diagnosis of Castleman’s disease with elevated IL-6 level was suspected; however, the present case had normal range of IL-6." (PMID 33730266, 2021). "Siltuximab is an anti-IL-6 immunoglobulin G-k monoclonal antibody that specifically binds to IL-6 and neutralizes its biological activity; it was approved in the USA in 2014 with restriction to the treatment of Castleman disease." (PMID 33384605, 2020). "The IL-6 inhibitor, siltuximab, has a therapeutic effect in Castleman disease and certain inflammatory diseases by neutralizing IL-6 production." (PMID 31148951, 2019). "Castleman disease patients present with iron-refractory hypochromic microcytic anemia, which develops in response to IL-6-mediated upregulation of hepcidin." (PMID 30469435, 2018). "Still, anti-IL-6 therapeutics are able to neutralize IL-6 production in vivo and are safe and useful in inflammatory diseases and Castleman disease." (PMID 30671025, 2018). "First, IL-6 inhibition is expected to affect diseases that can be pathologically related to long-term IL-6 action, such as Castleman disease and amyloid A amyloidosis." (PMID 30423923, 2018). "Subsequently, a phase II double-blind placebo-controlled trial on depressive symptoms analyzed the effect of anti-IL-6 Ab sirukumab on RA and siltuximab on Castleman disease." (PMID 30423923, 2018). "Accordingly, hypergammaglobulinemia is typically observed in patients with Castleman disease, a condition involving the continuous production of IL-6 from affected lymph nodes." (PMID 30423923, 2018). "Several previous studies examined potential cellular sources of IL-6 production in unicentric and multicentric Castleman's disease using in situ hybridization and immunohistochemistry." (PMID 29467920, 2018).
Castleman disease (continued). "The large amount of IL-6 from affected lymph nodes induces a type of systemic edema, called anasarca, massive ascites fluid and pleural effusions that are observed in Castleman disease and TAFRO syndrome." (PMID 30423923, 2018). "Increased IL-6 levels have been observed in Castleman’s disease, which is a poorly understood lymphoproliferative disorder driven by proinflammatory hypercytokinaemia." (PMID 30547812, 2018). "Castleman’s disease (CD) is an uncommon, heterogeneous lympho-proliferative disorder leading to high circulating levels of interleukin-6 (IL-6) and vascular endothelial growth factor (VEGF)." (PMID 28183278, 2017). "Castleman disease is a rare lymphoproliferative disorder that is characterized by the unregulated overproduction of interleukin-6 (IL-6)." (PMID 28287424, 2017). "Siltuximab (CNTO 328) is a chimeric anti–IL-6 mAb that has recently been approved for multicentric Castleman's disease, a rare B-cell lymphoproliferative disorder." (PMID 26840088, 2016). "Supporting evidence is provided by studies with multicentric Castleman disease patients who were treated with therapeutic monoclonal antibodies against IL-6 receptor (tocilizumab) or IL-6 (siltuximab)." (PMID 27445804, 2016). "Lymphoproliferation in Castleman’s disease is thought to be driven by IL-6, a cytokine produced by various cells including T cells and B cells in response to various inflammatory disease processes." (PMID 25884809, 2015). "Treatment with siltuximab, an anti-IL-6 monoclonal antibody with high affinity for human IL-6, has demonstrated efficacy in patients with Castleman disease treated in a phase 1 clinical trial." (PMID 26327301, 2015). "We have previously reported on a phase 1 study comprising 37 patients with Castleman disease treated with the anti-IL-6 monoclonal antibody siltuximab, which directly neutralizes IL-6, a key cytokine in the pathogenesis of MCD." (PMID 26327301, 2015). "Our patient had the multicentric type of Castleman’s disease, for which he received siltuximab, an anti-IL-6 antibody." (PMID 25884809, 2015). "Recently, therapies that target interleukin-6 or its receptor have been shown to be effective in Castleman’s disease." (PMID 25884809, 2015). "The overall pattern of normalisation in haematological parameters engendered by tocilizumab is in keeping with previous reports with this therapy in Castleman’s disease and strongly supports a role for IL-6 in the inflammatory anaemia of RA." (PMID 24295403, 2013). "Some speculate that upstream signaling molecules may influence interleukin-6 activity, which drives B-cell differentiation into plasma cells, in a manner similar to cytokine effects observed in Castleman disease." (PMID 41585370, 2026). "Siltuximab is currently the only FDA-approved IL-6 blocker for Castleman disease." (PMID 41567192, 2025). "In Castleman disease, gastrointestinal tumors and myeloproliferative neoplasms, a significantly positive correlation was found between elevated platelet counts and serum IL-6." (PMID 40160330, 2025). "In contrast, the multicentric variants of Castleman disease both the HHV8-positive cases and iMCD are associated with generalized symptoms and laboratory abnormalities which require systemic treatment, primarily anti-IL-6 therapy." (PMID 39252787, 2024). "Therapeutic targeting of IL-6 in chronic inflammatory diseases mainly relies on the two IL-6R antibodies tocilizumab and sarilumab, while the siltuximab directed against IL-6 has been approved for Castleman’s disease." (PMID 37838173, 2023). "Although the etiology of Castleman’s disease remains unclear, elevated levels of IL-6 are significantly correlated with symptom severity in this condition." (PMID 34253862, 2021). "Deregulation of IL-6 production has been shown to play a pivotal role in inflammatory autoimmune diseases like RA, juvenile idiopathic arthritis, adult-onset Still’s disease, giant cell arteritis, and Castleman disease." (PMID 35126375, 2021).
Castleman disease (continued). "Targeting IL-6 can been achieved by biological reagents, namely monoclonal antibodies directed against IL-6 itself such as siltuximab, which is approved for multicentric Castleman’s disease and has shown efficacy in RA." (PMID 32718086, 2020). "Castleman disease (CD), also known as angiofollicular hyperplasia, is a rare disorder characterized by nonmalignant mediastinal lymph node enlargement provoked by excess interleukin-6 (IL-6) secretion." (PMID 32399323, 2020). "IL‐6 is also believed to play an essential role in Castleman disease." (PMID 32990359, 2020). "In addition, tocilizumab, as well as the anti-IL-6 antibody siltuximab, lowered hepcidin and ameliorated anemia in multicentric Castleman disease patients." (PMID 30469435, 2018). "Secondly, diseases for which the IL-6 level is correlated with disease activity may be ameliorated by IL-6 inhibition, as evidenced by Castleman disease, RA, sJIA and large vessel vasculitis." (PMID 30423923, 2018). "The first clinical success with TCZ was observed with Castleman disease, which was a good candidate for IL-6 inhibition because continuous production of IL-6 from affected lymph nodes is suggested to be responsible for the systemic inflammation that occurs in this disease." (PMID 30423923, 2018). "A complex cytokine and chemokine network, including VEGF, IL-6, and IL-1, may play an important role in the development of Castleman’s disease." (PMID 29179528, 2017). "In three small clinical trials, IL-6 blockers, and IL-1ra-treatment, were effective in decreasing disease activity and in alleviating fatigue when used for treating IL-6-mediated Castleman’s disease." (PMID 28542626, 2017). "Since IL-6 drives Castleman’s disease, these observations may provide a mechanistic link between the two disorders." (PMID 25884809, 2015). "Castleman disease, a rare disorder biologically characterized by raised serum IL-6 levels, was excluded on the basis of clinical features, unremarkable total-body (18F)-fluorodeoxyglucose-positron emission tomography/computed tomography, and absence of serum HHV8 DNA and anti-HHV8 antibodies." (PMID 23432807, 2013). "Reasonably, EBV located within germinal centers may promote production of IL-6, subsequently leading to the development of Castleman disease." (PMID 19589162, 2009). "A key event in the pathogenesis of Castleman's disease has been recently suggested to be and abnormal production of a B cell growth factor such as IL-6 (Interleukin 6), leading to lymphoproliferation and plasma cell differentiation and being involved in the pathogenesis of plasmacytomas." (PMID 19019227, 2008). "Likewise, a systemic inflammatory syndrome in the absence of Castleman's disease has been described in HHV-8-infected patients in association with elevated viral IL-6 levels." (PMID 25133669, 2014). "We hypothesized that interleukin-6/interleukin-6 receptor/gp130 polymorphisms contribute to increased interleukin-6 and/or other components of the interleukin-6 signaling pathway in HIV-negative Castleman Disease patients." (PMID 23372742, 2013). "Effective anti-IL-6 agents have been developed and, to date, the monoclonal antibodies (mAb) tocilizumab (anti-IL-6R) and siltuximab (anti-IL-6) are approved by the FDA for the treatment of RA and Castleman’s disease, respectively." (PMID 36140335, 2022). "Serum IL-6 and CRP concentrations drop rapidly after resection of lymphadenopathy in patients with unicentric Castleman disease, which brings relief of its clinical symptoms." (PMID 34208103, 2021). "Siltuximab (CNTO 328), an anti-IL-6 monoclonal antibody, was approved by the FDA for treatment in patients with multicentric Castleman’s disease." (PMID 32824865, 2020). "This provided the initial information on the effect of IL-6 inhibition on inflammatory conditions and TCZ was approved for Castleman disease in 2005 in Japan." (PMID 30423923, 2018).
Castleman disease (continued). "Children with Castleman’s disease require a TCZ dosage of 8 mg/kg weekly because in this systemic diseaselymphocytes and macrophages of the affected lymph nodes continuously produce IL-6." (PMID 25685108, 2015). "As patients were initially managed as malignant sarcomas, certain Castleman disease-related details (e.g., human herpes virus 8 status, serum immunoglobulin G, interleukin-6 levels) were lacking." (PMID 39301171, 2024). "Corticosteroid monotherapy successfully reduced the edema, proteinuria, and IL-6, but hypoalbuminemia was not sufficiently improved due to castleman's disease and remission of the nephrotic syndrome was not achieved." (PMID 36873956, 2023). "Rapid production of IL-6 contributes to host defense during infection and tissue injury, but excessive IL-6 synthesis is involved in the pathogenesis of various diseases, such as SJIA, KD, Castleman disease, COVID-19 infection, etc.." (PMID 37608293, 2023). "The findings for our patients support that DADA2 patients without a Castleman disease-like phenotype are less responsive to anti-IL-6 therapy." (PMID 33757531, 2021). "Castleman disease (CD) is a rare systemic condition characterized by nonmalignant mediastinal lymph node enlargement prompted by excess interleukin-6 (IL-6) secretion." (PMID 32399323, 2020). "The pathogenesis of Castleman’s disease is not clear, but the recognized central factors include immune dysfunction, elevated interleukin-6 (IL-6) levels and HHV-8 infection in MCD have been well demonstrated." (PMID 31439011, 2019). "The over-expression of IL-6 mRNA was not confirmed in tissue samples of Castleman's disease by either in situ hybridization or quantitative real-time PCR." (PMID 29467920, 2018). "Siltuximab is an IL-6 targeted monoclonal antibody that has been approved by numerous regulatory bodies including the Food and Drug Administration (FDA) in the treatment of Castleman’s disease who are negative for HIV and human herpesvirus-8." (PMID 32707537, 2020).
tuberculosis (149 papers, 2008 to 2026). A chronic, recurrent infection caused by the bacterium Mycobacterium tuberculosis. "Patients with tuberculosis-associated COPD (T-COPD) were found to have higher levels of inflammatory markers such as IL-6, C-reactive protein, and NLR than patients with smoking-associated COPD." (PMID 40141021, 2025). "The mutant mice deficient in IL-6 production were also extremely susceptible to tuberculosis disease progression." (PMID 39514524, 2024). "Subjects with SNPs associated with decreased IL-6 classical signaling have lower odds of tuberculosis disease." (PMID 39114667, 2024). "The polymorphisms of IL6 and TNFα are closely linked to the development of tuberculosis, and TNFα serves as a protective factor against pulmonary tuberculosis." (PMID 39015338, 2024). "In study groups of tuberculosis patients from the same region in Ghana, we detected constitutive STAT3 phosphorylation in T cells from tuberculosis patients associated with high IL-6 plasma concentrations." (PMID 36650358, 2023). "Own previous studies provided evidence that aberrant high serum cytokines (i.e., IL-6, IL-10) in tuberculosis can affect T-cell functions, e.g., by causing constitutive STAT3 phosphorylation, in tuberculosis patients." (PMID 35759173, 2023). "The association between aberrant high plasma IL-6 levels and impaired T-cell functions in tuberculosis patients confirmed our previous findings." (PMID 36650358, 2023). "This association remained significant after adjusting for markers of disease severity and suggests an independent predictive role of baseline IL-6 for risk-stratification in tuberculosis patients." (PMID 34711538, 2022). "Despite these limitations, our study found a significant and generalizable association between high baseline IL-6 concentrations and subsequent unfavorable tuberculosis treatment outcomes in a relatively large and epidemiologically diverse population." (PMID 34711538, 2022). "Across the three independent cohorts analyzed in our study, we found a consistent association between higher baseline IL-6 concentrations and subsequent unfavorable tuberculosis treatment outcomes." (PMID 34711538, 2022). "Application of IL-6 inhibitors in a clinical setting demonstrated an increased risk of infections, including tuberculosis." (PMID 35154093, 2022). "External validation among predominantly diabetic tuberculosis patients found an association between pre-treatment IL-6 concentrations and subsequent recurrence and death." (PMID 34711538, 2022). "Phenotypic and functional changes in adaptive and innate immune cells provide a complex picture of tuberculosis pathognomonic mechanisms potentially caused by aberrantly high IL-6 and IL-10 levels." (PMID 34035497, 2021). "For rs2069837 in IL6, found that the risk of tuberculosis in individuals carrying risk allele G was 1.88 times in log-additive model (OR = 1.88, 95% CI = 1.54–2.30, p = 6.83E-10)." (PMID 29662655, 2018). "The present study was aimed to evaluate the levels of TNF-α, IL-10 & IL-6 cytokines and their correlation with genotype variants amongst tuberculosis patients and their household contacts." (PMID 26359865, 2015). "In fact, it has been reported that IL-6 blockade increased susceptibility to tuberculosis in IL-6-deficient mice and anti-IL-6 antibody-treated mice." (PMID 21603208, 2011). "In addition to TNF- α, increased Interleukin-6, Interleukin-8, and Interleukin-12(IL-6,8 and 12) levels have been linked to the formation of cavities, bronchial wall thickening, and fibrotic bands in individuals with active tuberculosis." (PMID 37303367, 2023). "Similarly, external validation among predominantly HIV coinfected tuberculosis patients found an association between pre-treatment IL-6 concentrations and subsequent treatment failure and death." (PMID 34711538, 2022).